PHIP (PHIP subunit of CUL4-Ring ligase complex)
Diseases named in the same sentence as PHIP in open-access papers (continued):
Sharing a sentence is not in itself a finding about the gene and the disease.
cancer (22 papers, 2012 to 2026). A tumor composed of atypical neoplastic, often pleomorphic cells that invade other tissues. "These insights can improve the accuracy of using hair PhIP levels as a biomarker for exposure and its potential associations with cancer risk." (PMID 39853040, 2025). "The last target of DEmiRNA identified in this study was the PHIP gene, which encodes the pleckstrin homology domain interacting protein, which is involved in multiple biological processes, including cancer pathogenesis, cell cycle control and metabolism." (PMID 38474013, 2024). "Evidence has shown that the ability of PhIP forming DNA-adduct by altering the DNA sequence in human body is the main cause of cancer." (PMID 31652883, 2019). "According to the International Agency for Research on Cancer (IARC), PhIP is classified as probable carcinogen and may cause human cancer (Class 2B) with its LD50 estimated to be 3 mg/kg." (PMID 31652883, 2019). "Collectively, we identify PHIP as a regulator of the interplay between distinct chromatin regulators that function in development and disease and as a targetable vulnerability in cancers with broad SWI/SNF inactivation." (PMID 41946722, 2026). "Three unrelated protein targets linked to cancer or inflammation (SMYD3, NUDT5, and PHIP) were selected." (PMID 39966348, 2025). "PhIP has previously been shown to be genotoxic producing DNA adducts and contributing towards the formation of dietary cancers." (PMID 32342131, 2020). "Nonetheless, the observation that PhIP is mediating gene expression changes within the adipocyte, and that the pathways most affected are related to cancer and other chronic disease is intriguing." (PMID 27547236, 2016). "PhIP mediates gene expression changes within the adipocyte, and the pathways most affected are related to cancer and other chronic diseases." (PMID 27547236, 2016). "PhIP is widely believed to induce cancer after undergoing a number of metabolic activating events in which its metabolites adduct to DNA and cause DNA mutations." (PMID 24312188, 2013). "To both elucidate these mechanisms and identify vulnerabilities caused by these mutations, we leverage genome-wide CRISPR-Cas9 screening in hundreds of cancer cell lines and identify the chromatin reader protein PHIP as a specific dependency in cancers with broadly disrupted SWI/SNF function." (PMID 41946722, 2026). "Pleckstrin homology domain-interacting proteins (PHIP) have previously been shown to be potential targets for pancreatic and several other different cancer types; a very recent study showed that PHIP also acted on the focal adhesion complex and drove glioblastoma invasion." (PMID 35053605, 2022). "Since PTHrP reportedly increased the cancer cell expression of IL-8, this study evaluated whether PhIP increased the inductive effect of 786-O cells on osteoclastogenesis by targeting the PTHrP/IL-8 loop." (PMID 31569368, 2019). "Importantly, PhIP’s specificity for ER-α appears to be a key activity in its ability to drive the cancer process." (PMID 29362861, 2018). "In addition to the effects that were observed with consumption of tomato + broccoli on PhIP-induced prostate carcinogenesis in this study, we also observed a profound effect on other known sites of PhIP-induced cancers." (PMID 24312188, 2013). "To clarify whether the PhIP levels in rat fur samples represented the exposure level to PhIP in target tissue, we also examined PhIP-DNA adduct levels in the rat colon, a target organ for putative HAA-associated cancer, and observed a similar pattern of PhIP levels as those detected in rat fur." (PMID 34315542, 2021). "Given that induction of colonic DNA adduct formation (i.e., early cancer marker) occurs 24 h after PhIP treatment and the adducts are generally repaired by a DNA repair system, the increase in OXPHOS might be a result from a compensatory response to excessive ATP consumption." (PMID 32927802, 2020).
cancer (continued). "Although the apparent toxic effects of combined PhIP and tomato + broccoli need additional study, the results of this study support the hypothesis that a diet rich in tomato and broccoli can reduce or prevent dietary carcinogen-induced cancers." (PMID 24312188, 2013). "Thus, PhIP was acting as both an initiator and a lobe-specific cancer promoter." (PMID 24312188, 2013). "Thus, a probe molecule that is specific to PHIP could open the way towards novel and broad-based chemotherapy against non-targetable tumors and/or facilitate the understanding of the biology behind these cancers." (PMID 35426591, 2022). "Since, Curcuma drugs suppressed activity and expression of CYP3A4 in intestinal epithelial cells, our observation that GLT down-regulates PhiP/DSS-dependent expression of CYP3A4 in vivo, further confirms cancer preventative activities of GLT." (PMID 23118901, 2012). "PhIP also did not induce cancer in cynomolgus monkeys employing the same doses and regimens as for IQ and MeIQx." (PMID 34271992, 2021). "For instance, CYPs (e.g., CYP1A2) catalyze 2-hydroxylation of estradiol in which the product (i.e., 2-methoxyestradiol) inhibits cancer cell proliferation, suggesting reduced CYP1A2 activity due to PhIP exposure may trigger carcinogenesis." (PMID 32927802, 2020).
neurodevelopmental disorder (5 papers, 2024 to 2026). A behavioral and cognitive disorder with onset during the developmental period that involves impaired or aberrant development of intellectual, motor, or social functions. "An additional patient with PHIP-associated neurodevelopmental disorder and unusual features due to a novel nucleotide change is illustrated here." (PMID 39594970, 2024). "However, PHIP’s chromatin binding is disrupted in neurodevelopmental disorders." (PMID 38474013, 2024).
infection (2 papers, 2016 to 2021). The state of being infected such as from the introduction of a foreign agent such as serum, vaccine, antigenic substance or organism. "As well, ectopic expression of a PHIP C-terminal truncation mutant, lacking the same functional regions as predicted from the human mutation identified in BL, did not lead to accelerated tumorigenesis following infection of Eμ-Myc HSPCs." (PMID 27982060, 2016).
gastrointestinal tumors (1 paper, 2013). "In stark contrast, none of the tomato + broccoli + PhIP animals died or needed to be euthanized early due to gastrointestinal tumors." (PMID 24312188, 2013). "It should be noted that many of the PhIP-alone treated animals with gastrointestinal tumors did not survive to the end of the 52 week study (average time to death of 46.8±4.3 weeks)." (PMID 24312188, 2013).
haematological disorders (1 paper, 2021). "In contrast, to the best of our knowledge, mutations in PHIP and KLC2 have not been reported in the context of haematological disorders." (PMID 33990592, 2021).
PHIP also shares sentences with these, for which no sentence is quoted: erythroleukemia (2 papers); metastatic melanoma (2); adenocarcinoma (1); atrial fibrillation (1); bacterial infection (1); Brain atrophy (1); Cabezas syndrome (1); cardiac hypertrophy (1); cutaneous melanoma (1); depression (1); dilated cardiomyopathy (1); glioblastoma (1); glioma (1); hepatoma (1); hypertrophic cardiomyopathy (1); Insulin resistance (1); intellectual impairment (1); metabolic disease (1); metastasis (1); Neurodevelopmental delay (1); non-small cell lung carcinoma (1); obesity syndromes (1); Prader-Willi syndrome (1); prostatic intraepithelial neoplasia (1); rectal cancer (1); small cell lung carcinoma (1); Stroke (1).